Y_RNA (Y RNA )
Gene: Miscellaneous RNA gene on chromosome 3 (23,273,807 to 23,273,910, forward strand). Ensembl gene ENSG00000206728.
Homologues: Orthologues: chimpanzee Y_RNA (99% identical), macaque Y_RNA (89% identical), guinea pig Y_RNA (87% identical). Paralogues in human: Y_RNA (86% identical), RNY3 (85% identical), Y_RNA (85% identical), Y_RNA (84% identical), Y_RNA (83% identical), Y_RNA (82% identical), RNY3P1 (81% identical), RNY3P4 (81% identical), Y_RNA (81% identical), Y_RNA (80% identical), RNY3P11 (79% identical), RNY3P14 (79% identical), and 93 more.